EGFR (epidermal growth factor receptor)
Diseases named in the same sentence as EGFR in open-access papers (continued):
Sharing a sentence is not in itself a finding about the gene and the disease.
glioma (continued). "Tyrosine kinase signal transduction pathways, especially epidermal growth factor receptor (EGFR) driven proliferation play an integral role in the pathogenesis of gliomas." (PMID 22479427, 2012). "In contrast, it is well known that activation of the receptor tyrosine kinases such as epidermal growth factor receptor (EGFR) is the most frequent molecular aberration found in high-grade gliomas." (PMID 23050879, 2012). "Among these pathways we found several expected key players such as EGFR and Insulin Receptor signaling pathways, RAS signaling, as well as a glioma-associated regulation of transforming growth factor-β2 production and SMAD pathway." (PMID 21390271, 2011). "Utilizing pathway information from DAVID, we found that the subnet with EGFR as a target gene was highly enriched with glioma genes (p<0.004), the MAPK signaling pathway (p<0.02), and pathways in cancer in general (p<8×10−8)." (PMID 21390271, 2011). "In glioblastoma multiforme (glioma), a highly malignant and lethal neoplasm of the brain, amplification of the EGFR gene leads to overexpression of the receptor and is associated with a number of mutations." (PMID 24212795, 2011). "The most studied is the epidermal growth factor receptor (EGFR) that was early recognized in gliomas." (PMID 22091432, 2011). "The epidermal growth factor receptor (EGFR) has been implicated in the development of a wide range of human cancers including breast, glioma and lung." (PMID 21915281, 2011). "In 2008, Contessa and colleagues reported that inhibition of N-linked glycosylation reduced RTK (i.e. EGFR, ErbB2, ErbB3 and IGF-IR) signaling through AKT and radiosensitized tumor cells in glioma and pancreatic adenocarcinoma cell lines." (PMID 22192458, 2011). "The overall results of this study revealed a role for EFEMP1 in the suppression of glioma growth, via independent blockade of EGFR and AKT signaling pathways and the repression of VEGFA-induced angiogenesis." (PMID 21955618, 2011). "Gliomas are frequently characterized by dysregulated signaling downstream of growth factor receptors such as EGFR, PDGFR, and IGFR, and elevated production of their corresponding ligands." (PMID 21754979, 2011). "Several molecular and biochemical abnormalities such as specific chromosomal aberrations, upregulation of epidermal growth factor receptor (EGFR), loss of phosphate and tensin homology (PTEN), have been clearly associated with gliomas." (PMID 21884623, 2011). "Our data agrees with recent studies in EGFR driven gliomas models that show mTOR can be regulated by the PKC pathway independent of Akt phosphorylation." (PMID 21267448, 2011). "For example, EGFR amplifications are predominantly found in classical and neural subtypes or in cluster 18 gliomas." (PMID 24212656, 2011). "To date, unmodified RNA-aptamers have been selected against the purified extracellular domain of EGFR and then used for gold-nanoparticles delivery to cancer cells or, in a surface-immobilized form, to capture EGFR-expressing glioma cells." (PMID 21915281, 2011). "Deregulation of EGFR was shown to have critical role in gliomas as well as in several other malignancies." (PMID 21756334, 2011). "Most established GBM cell lines form discrete, non-invasive tumors with well-circumscribed borders that push aside rather than invade adjacent normal tissue and cannot maintain the overexpression of the key EGFR gene that can promote glioma cell invasion." (PMID 21314332, 2011). "EGFR has been a central focus of study in glioma due to its proposed role in the transformation and growth of glial tumors, and the fact that EGFR is the most commonly amplified gene in GBM." (PMID 20113523, 2010). "EGFR amplification and phosphatase tensin homolog on chromosome ten (PTEN) loss are two common genetic alterations seen in gliomas." (PMID 20975961, 2010).
glioma (continued). "An EGF-SubA fusion protein has recently been shown to kill EGFR-positive rat glioma and human breast and prostate cancer cells at picomolar concentrations." (PMID 20871837, 2010). "Although overexpression of the EGFR protein is observed in 40% of grade IV pediatric gliomas, EGFR gene amplification in children is very rare." (PMID 20652056, 2010). "In this investigation we employed brightly fluorescent, photostable quantum dots (QDs) to specifically target epidermal growth factor receptor (EGFR) that is upregulated in many gliomas." (PMID 20614029, 2010). "In five out of the six gliomas we analysed (tumours 4, 7, 21, 22 and 30) the amplification process involved sequences originating only from the 7p11 region, wherein lies the EGFR gene." (PMID 21170331, 2010). "Current research focuses on immunotherapy as a novel approach of targeted molecular therapies on glioma treatment, on the basis of the presence of potential antigens such as EGFR." (PMID 19293809, 2009). "While EGFR-Ras and PI3K are commonly upregulated in gliomas and experimental models demonstrate that these pathways are required for tumorigenesis, therapies that target EGFR and PI3K signaling have proven disappointing." (PMID 19214224, 2009). "Our study examined the role of nimotuzumab and cetuximab both, the two monoclonal antibodies (mAbs) to EGFR, as radiosensitisers in a murine glioma model in vivo." (PMID 19293809, 2009). "Through genetic analysis of our model, we identified crucial downstream effectors of EGFR and PI3K signaling, many of which are mutated and/or activated in human glioma." (PMID 19214224, 2009). "Analysis of the downstream signaling components of the PDGF proteomic group revealed generally lower PI3K/Akt activity than in the EGFR glioma group although S6 phosphorylation was paradoxically high." (PMID 19915670, 2009). "Using the same system, this group has described the production high grade gliomas by combining INK4a/ARF deletion with astrocyte specific overexpression of EGFR, or Ras and Akt." (PMID 19814820, 2009). "EGFR in the context of the human gliomas results in a strong stimulator of tumour cell migration and invasion." (PMID 19293809, 2009). "In glioma models, coactivation of EGFR-Ras and PI3K stimulates Tor, and in humans, Tor activity is correlated with poor patient prognosis." (PMID 19214224, 2009). "The set of overexpressed genes in gliomas with EGFR amplification was significantly enriched in genes located on chromosome 1 (305 genes, p < 10-4), chromosome 19 (151 genes, p < 10-4), chromosome 7 (109 genes, p < 10-4) and chromosome 4 (85 genes, p < 10-4)." (PMID 18492260, 2008). "In high grade gliomas, 1p19q codeletion and EGFR amplification are mutually exclusive and predictive of dramatically different outcomes." (PMID 18492260, 2008). "Weinvestigated pStat3 expression and itscorrelations with histological grade, EGFR aberrations,PTEN mutations, pAkt expression, cell proliferation, and apoptosis/autophagy in a series of gliomas." (PMID 19421400, 2008). "Doxycycline was studied in vitro using EGFR-transfected U251 glioma cells that secrete MMPs in order to evaluate the extent of MMP blockade." (PMID 18186943, 2008). "For example, among the neurofilament genes (INA, NEFH, NEFM, NEFL) present in cluster C, alphainternexin (INA) was the only one overexpressed in both gliomas with 1p19q codeletion and cortex samples in comparison to gliomas with EGFR amplification." (PMID 18492260, 2008). "Gliomas with EGFR amplification segregated from the cancer stem cells by one main gene cluster (I) enriched in genes involved in immune response (11 genes, p < 10-4), extracellular matrix (7 genes, p < 10-4) and angiogenesis (4 genes, p < 10-4)." (PMID 18492260, 2008).
glioma (continued). "The expression of EGFR is often amplified in human glioma, but is undetectable or weakly expressed in normal brain." (PMID 19018263, 2008). "The 1p19q codeletion and EGFR amplification are mutually exclusive and related to dramatically different outcomes in high grade gliomas." (PMID 18492260, 2008). "The fact that GSCs of both the SU-1 and SU-2 lines faithfully preserved the EGFR amplification and PTEN loss greatly enhances their utility in biological and preclinical studies of human gliomas." (PMID 18940013, 2008). "We performed a microarray gene expression study of four high grade gliomas with 1p19q codeletion and nine with EGFR amplification, identified by CGH-array." (PMID 18492260, 2008). "Gliomas with 1p19q codeletion and gliomas with EGFR amplification segregated into two distinct groups." (PMID 18492260, 2008). "In gliomas, it was observed that thelevels of pStat3, together with pAkt, correlate with EGFR aberrations, butspecifically with EGFRvIII expression." (PMID 19421400, 2008). "The G3 domain of versican induces glioma cell adhesion through EGFR and β1-integrin-mediated pathways." (PMID 17453002, 2007). "In fact responses to gefitinib were recorded for the first time and the importance of EGFRvIII expression (especially in presence of PTEN expression) on EGFR TKIs activity assessed in gliomas." (PMID 17353924, 2007). "Four commonly used EGFR-expressing glioma cell lines, U87, U251, SF763, and SF767, were examined for FABP7 expression using immunohistochemistry, and all these lines demonstrated both cytoplasmic and nuclear FABP7 immunoreactivity (data not shown)." (PMID 16623952, 2006). "The pan anti-EGFR antibody 528 significantly inhibited the growth of U87MG.de2-7 gliomas by day 14 (P<0.05); however, this growth inhibition was significant only to day 23 (P=0.023)." (PMID 15770208, 2005). "EGFR gene amplification and subsequent overexpression of the EGFR protein is particularly prevalent in gliomas, the most common primary tumour of the central nervous system." (PMID 15770208, 2005). "Epidermal growth factor receptor is rarely present in normal glial cells, but is expressed in human gliomas." (PMID 15305185, 2004). "In conclusion, this study provides evidence that EGFR plays an important role in the regulation of telomerase activity of glioma cells." (PMID 11953893, 2002). "Antisense-EGFR transfection in rat C6 glioma cells was also found to inhibit cellular proliferation and induce apoptosis." (PMID 11953893, 2002). "In this study, 24/213 (11%) glioma patients with presumed tumor predisposition carried GVs in CPGs that potentially sensitize them to targeted therapies not routinely used in glioma patients, such as PARP, immune checkpoint, EGFR, or CDK4/6 inhibitors." (PMID 41546701, 2026). "In the early stages of GBM, elevated expression of the epidermal growth factor receptor (EGFR) leads to β-catenin phosphorylation, which enhances its binding to calcium-binding proteins or increases its expression, subsequently facilitating glioma cell migration and EMT." (PMID 41141394, 2026). "EGFR is known to be overexpressed in various solid tumors, including gliomas." (PMID 40558363, 2025). "Furthermore, our previous studies reported that TMED2 enhances EGFR-AKT signaling in glioma by participating in EGFR recycling." (PMID 40519935, 2025). "TERT promoter mutations or EGFR amplification have not yet been described in the setting of NF1-associated gliomas, while alteration as a gain of chromosome 7 and loss of 10 were rarely observed." (PMID 40277798, 2025). "Notably, in low-grade gliomas, the combination of chromosome +7/-10 with TERT mutation or EGFR amplification is considered an independent molecular marker of the worst clinical outcome." (PMID 41201287, 2025).
glioma (continued). "Further experiments revealed that TSPAN13 knockdown increased glioma cell sensitivity to carmustine, another alkylating agent, while showing no significant impact on sensitivity to the apoptosis inducer cisplatin or the EGFR inhibitor gefitinib." (PMID 39903772, 2025). "The EGFR amplification results in overexpression of EGFR proteins in glioma cells." (PMID 40941753, 2025). "Moreover, in U-373 MG glioma cells SP induced tyrosine phosphorylation of several proteins including EGFR and activated the EGFR complex containing the adapter proteins Sos, Shc, and Grb2, but not c-Src." (PMID 39941886, 2025). "Importantly, TMED2 was demonstrated to promote glioma tumorigenesis by mediating EGFR recycling transport." (PMID 40497947, 2025). "Similarly, EGF stimulated EGFR in glioma cells which subsequently phosphorylated the carboxy terminal of the GluN2B subunit of NMDAR and enhanced glutamate-NMDAR signaling and then glioma cell migration." (PMID 40405084, 2025). "SP activates the MAPK pathway, increasing ERK2 kinase activity and DNA synthesis in glioma cells, and EGFR is an essential regulator in SP/NK-1R-induced activation of the MAPK pathway and cell proliferation in U-373 MG glioma cells, and these events are mediated by subunit Gαi protein." (PMID 39941886, 2025). "Notably, glioma-derived EVs are characterized by elevated expression levels of GBM-specific markers, EGFR and EGFRviii, suggesting that these EGFR and EGFRviii+ EVs are not only derived from gliomas but are also likely to originate from the brain." (PMID 39742488, 2025). "In this work, the epidermal growth factor receptor (EGFR) is considered as a significant biomarker of the aggressive development of the tumor process, the overexpression of which is associated with accelerated division and proliferation of glioma cells." (PMID 41473440, 2025). "Anti-EGFR DNA aptamers are promising MoREs for targeting glioma cells." (PMID 40943631, 2025). "Combined with single-cell sequencing technology, Tirosh and his collaborators further revealed that there are complex developmental hierarchies and cell state variations within gliomas, and that the activity of the EGFR/MAPK pathway is highly heterogeneous in different cell subpopulations." (PMID 40630952, 2025). "Alisertib inhibits glioma cell proliferation and induces B7-H3 expression via EGFR activation." (PMID 39928563, 2025). "Thus, the aim of this study was to determine the potential antineoplastic effect of scutellarin and its combination with lidocaine on human glioma, and explore the link between the anti-glioma effect and EGFR signaling." (PMID 39888904, 2025). "This pattern is consistent with previous reports in the literature, where GPC1 membrane protein was found to be highly expressed on the tMV surface in pancreatic cancers, and plasma membrane receptors such as EGFR and EGFRvIII were upregulated in the MV fractions from cancer cells in glioma tumors." (PMID 40285610, 2025). "A recent study revealed that melatonin may amplify Nimotuzumab’s anti-glioma efficacy by inhibiting epidermal growth factor receptor (EGFR) dimerization." (PMID 40427575, 2025). "The prognosis of glioma patients varies significantly and is influenced by factors such as tumor grade, isocitrate dehydrogenase (IDH) mutation, and epidermal growth factor receptor (EGFR) amplification." (PMID 40094001, 2025). "The pairing of enzalutamide with an EGFR-targeted agent, such as afatinib, may enhance antitumor efficacy in glioma cells by simultaneously targeting both signaling pathways." (PMID 41153666, 2025). "The proportion of EGFR+ tumor cells was significantly elevated in high‐grade gliomas, suggesting that the proportion of EGFR+ tumor cells could serve as an indicator of disease progression." (PMID 40264576, 2025). "Notably, in IDH1/2-mutant glioma, CDKN2A/B deletion and EGFR amplifications were rare but confined to high-grade gliomas." (PMID 41377022, 2025).
glioma (continued). "The EGFR/PI3K/AKT pathway is involved in lipid metabolism in glioma and promotes tumor growth." (PMID 41244832, 2025). "The lifting of PRC2-mediated repression unleashes a cascade of pro-tumorigenic events: formerly silenced oncogenic factors become active, which in turn drive the formation of glioma-specific super-enhancers and up-regulate oncogenes such as EGFR, miR-21, and WEE1." (PMID 41154382, 2025). "Glioma-myeloid and myeloid-glioma signaling identified EGFR, SPP1, MIF, and other important LRI." (PMID 40191211, 2025). "This study highlights the challenges in diagnosing EGFR amplification status in recurrent gliomas." (PMID 40197845, 2025). "Additionally, pathways associated with tumor progression and drug resistance, such as EGFR tyrosine kinase inhibitor resistance, glioma, renal cell carcinoma, and efferocytosis, were also notably suppressed." (PMID 40918260, 2025). "About 50% of glioma patients exhibit amplification of the EGFR gene, which can be diagnosed and further used to differentiate the malignancy levels of tumors through the detection of Exo-EGFR." (PMID 39465690, 2025). "In addition, EGFRvIII mutation is associated with glioma WHO grading, molecular subtypes, IDH mutation, and EGFR amplification status." (PMID 40527884, 2025). "An aptamer specifically binding to the mutant EGFR ([68Ga]-NOTA-EGFRvIII) was tested in a xenograft mouse cell model of U87MG glioma expressing either EGFR or EGFRvIII that was injected subcutaneously and showed binding to EGFRvIII but no binding to conventional EGFR on micro-PET imaging." (PMID 41473440, 2025). "EGFR BATs infusions induced increases in glioma specific anti-tumor cytotoxicity by peripheral blood mononuclear cells (p < 0.03) and NK cell activity (p < 0.002) ex vivo, and increased serum concentrations of IFN-γ (p < 0.03), IL-2 (p < 0.007), and GM-CSF (p < 0.009)." (PMID 38263486, 2024). "In the conventional subtype of glioma, EGFR amplification is observed." (PMID 38686058, 2024). "LncRNA LPP-AS2 promoted glioma tumorigenesis via a miR-7-5p/EGFR/PI3K/AKT/c-MYC feedback loop." (PMID 38725030, 2024). "There have been studies on the targeted delivery of mTORC1/mTORC2 inhibitor-loaded liposomes to glioma cells or elongated survival after a treatment consisting of photodynamic therapy (PDT) and liposomes encapsulating lapatinib (an EGFR inhibitor) in glioma-bearing rats." (PMID 39200286, 2024). "The single-cell data suggested that EGFR was primarily expressed in glioma cells." (PMID 38515213, 2024). "In glioma, a truncated and oncogenic form of the epidermal growth factor receptor (EGFR), known as EGFRvIII, was demonstrated to be present in microvesicles derived from tumour cells; these microvesicles can then transfer EGFRvIII to neighbour cells to activate downstream AKT signalling." (PMID 38802766, 2024).